CD163 (CD163 molecule)
Diseases named in the same sentence as CD163 in open-access papers (continued):
Sharing a sentence is not in itself a finding about the gene and the disease.
tumor (continued). "When the CD163 protein was expressed in GC tissues with varying degrees of differentiation, the positive CD163 expression was restricted to the cytoplasm and the cell membrane, and the expression was more evenly distributed in the tumor mesenchyme." (PMID 41142606, 2025). "CD163 functions as a hemoglobin-haptoglobin complex receptor and is associated with the “M2” or “pro-tumor” state of macrophages whereas normal microglia do not express CD163." (PMID 40191733, 2025). "On the basis of our findings, TWEAK expression in the metastatic tumor cells may be minimal, and its secretion in CRLMs may be mainly mediated by inflammatory cells, such as Th17 cells and CD163‐positive macrophages, in the tumor microenvironment." (PMID 40629930, 2025). "We aim to determine changes and distribution of CD163+ immune cell levels in specific tumor regions (tumor nest and tumor stroma) of PT, LNM and DM, and evaluate potential associations of CD163 levels at these distinct sites with clinicopathological characteristics and survival (PFS and OS)." (PMID 39751847, 2025). "First, we assessed the expression of CD68 and CD163 in both normal and tumor mucosa." (PMID 41573553, 2025). "Our findings extend this knowledge by demonstrating that FGFR2 expression is positively correlated with markers of an immunosuppressive TIME, namely CD163+ macrophages and FOXP3+ regulatory T cells, and that these associations are particularly evident in luminal A tumours." (PMID 41018083, 2025). "The tumor cells were positive for CD163, ALK, phosphorylated ERK, and cyclin D1." (PMID 40361876, 2025). "Conversely, CD163, a surface receptor characteristic of anti-inflammatory M2 macrophages, contributes to the establishment of an immunosuppressive microenvironment that facilitates tumor progression." (PMID 39857116, 2025). "In each tumor component, the prognostic impact of CD163 and CSF-1 was examined." (PMID 39488822, 2025). "These crucial findings are supported by identification of increased levels of tumor-promoting CD68+CD163+ M2-like MPs, together with Rep expression, as well as increased detection of markers for oxidative DNA damage (8OHdG), most probably evoked by inflammation-driven radical formation." (PMID 40136704, 2025). "Suppressive CD68+CD163+ macrophages in the tumor near normal tissue were relatively abundant." (PMID 40498004, 2025). "Therefore, CD163+ TAMs have been proposed as tumor biomarkers, while their potential as targets for anti-cancer immunotherapeutic approaches is high and worth exploring." (PMID 39451197, 2024). "Furthermore, we identify tumor microenvironment biomarkers of increased stiffness, including αSMA + myogenic fibroblasts, CD163 + macrophages, and HABP (hyaluronic acid binding protein)." (PMID 38914647, 2024). "Tumor necrosis was observed in the 2‐ME group which could be as a result of the lower CD163+ cell numbers present in the TME." (PMID 38600057, 2024). "Therefore, CCL2 will likely be crucial in recruiting the CCR2+ monocytic precursors of CD163+ TAMs to tumours, as reported for CCR2+ MDSCs." (PMID 38903497, 2024). "Through mIF and IHC techniques applied to the Renji TMA cohort, we were able to identify the presence of PLOD2 + SAA1 + ccRCC cells and we found this tumor subclusters were related with high infiltration of CD163 + macrophages and Treg cells, indicating the establishment of an immunosuppressed TME." (PMID 38951896, 2024). "Only for one tumor, CD163+macrophages seemed limited to the invasive margin (P05)." (PMID 39053947, 2024). "PD-L1 expression on tumor cells was strongly correlated with the infiltration of CD163+ macrophages (r = 0.8582, p < 0.0001), and PD-L1 expression on interstitial cells was moderately related to the infiltration of CD163+ macrophages (r = 0.4232, p < 0.0001)." (PMID 38970071, 2024).
tumor (continued). "Importantly, we show that CAF-derived sialic acids influence the differentiation of monocytes to CD163+CD206+ macrophages, a phenotype associated with tumor-promoting immunosuppressive TAMs." (PMID 38594506, 2024). "The authors suggest a possible role of CD163+ in tumor cell and macrophage infiltration in rGBM." (PMID 39409905, 2024). "CD163+ M2-type macrophages promote tumor growth, invasion, and metastasis." (PMID 39272861, 2024). "Considering eHSP90α is a potent inducer of macrophage M2-polarization, we also noticed that HH01 treatment led to an obvious increase in tumor F4/80+ pan-macrophage levels but a reduction in CD163+ M2-macrophages, resulting in a significant decrease of the ratio of M2-macrophage to pan-macrophage." (PMID 38994997, 2024). "Protumor influence of CD163+ TAM may be a consequence of their involvement into enhanced tumor cell invasion, proliferation, angiogenesis, and metastasis along with inhibition of antitumor T-cell responses." (PMID 38287290, 2024). "Therefore, the concept that monocytes recruited into tumours differentiate into proliferating CD163+ TAMs with immunosuppressive properties concurs with both published murine data and recent single-cell data from human tumours." (PMID 38903497, 2024). "In addition, we confirmed the correlation between CD163 expression and the lymphatic system by analyzing matched tumor-free and metastatic lymph nodes from the same patients." (PMID 38407373, 2024). "Likewise, overweight/obese patients showed a strong tendency for higher numbers of CD68+ (1.8-fold, p = 0.119) and CD163+ (3.80-fold; p = 0.062) cells in the tumor tissue." (PMID 39456610, 2024). "Neighborhoods located in the tumor center were quite heterogeneous with various cell types present, however, often Tregs (P05, P16), CD163+macrophages (P09, P12, P13, P16) alone or together (P18-P20, P25, P29) were mostly present in neighborhoods localized in the tumor center." (PMID 39053947, 2024). "Increased numbers of CD68+/PDL1+/CD163- cells at intratumoral sites but not in tumor stroma were associated with favorable clinical outcomes." (PMID 39044824, 2024). "Various mechanisms were hypothesized for the emergence of macrophages that co-express CD163 and PD-L1, including the proposed mechanism wherein B7-H3 expression by tumor cells reduces the peritumoral immune response and induces CD163+ macrophages." (PMID 38893259, 2024). "The number of infiltrating CD163+ macrophages into tumor was counted under microscopy." (PMID 38745748, 2024). "CD163+macrophages as well as Tregs had the highest tendency to infiltrate the tumor center where they likely suppress antitumor immune functions or promote tumor progression." (PMID 39053947, 2024). "By employing single-cell analysis, we identified immunosuppressive LAMP3+ cDCs, likely promoting TREG migration into tumor tissues through the CCL17-CCR4 axis, in addition to increased CD163-positive macrophages previously associated with adverse TFHL prognoses." (PMID 38012392, 2024). "Collectively, these results support the notion that CD163+ TAMs contribute to tumour progression." (PMID 38903497, 2024). "Fewer CD163(+) M2 macrophages were detected in the shMCT-1 tumor than the scramble tumor." (PMID 38505617, 2024). "It is a well-known fact that macrophage is the most plentiful and important tumor-infiltrating immune cell type, and it would be differentiated into M2-like tumor-associated macrophage (TAM) expressing CD68+, CD163+, and CD204+ in the local milieu of OSCC stromal spaces." (PMID 38671413, 2024). "Thus, samples from overweight/obese patients were characterized by a distinct increase in CD163+ M2-like polarized macrophages, which was particularly pronounced in tumor-adjacent adipose tissue." (PMID 39456610, 2024). "Thus, CD47, CD68, and CD163 not only serve as prognostic indicators but also represent promising targets for novel cancer therapies designed to modulate the tumor immune microenvironment." (PMID 39682556, 2024).
tumor (continued). "Furthermore, we found a strong association correlation between +CD163 + CD204M2-TAM with STAT3 and NF-κB signaling pathways, as well as with factors linked to tumor growth, dissemination, and immunosuppression." (PMID 39061137, 2024). "In HCC, which associates with secretion of chemokines and growth factors by the stromal cells and tumor cells, monocyte-derived macrophages can acquire a phenotype of Kupffer cells and may start expression of putative markers, including CD163." (PMID 38287290, 2024). "In addition, the CD206 expression of CD68+CD206+M2 TAMs closer to the tumor cells was lower, while the expression of CD163 and CD206 on TAMs was negatively correlated." (PMID 38279145, 2024). "Additionally, CD68 in the middle of the tumor exhibited moderately positive and significant correlations with CD163 at the margin (p value = 0.0003) and PD-L1 expression (p value = 0.0409)." (PMID 39338178, 2024). "There are pieces in the puzzle of the role of sCD163 missing, especially regarding its impact in the tumor microenvironment and in other tissues and organs, while ectopic expression of its precursor protein, CD163, from tumor cells needs to be taken into consideration." (PMID 39451197, 2024). "Increased numbers of CD163 TAMs and few CD8+ lymphocytes were immunohistochemically observed in clinical samples with PM, which suggested that TAMs were associated with the suppression of anti-tumor immunity." (PMID 38745748, 2024). "Moreover, Cd45, as a marker of leukocytes; F4/80, as a marker of tumor-associated macrophages (TAM); and Cd163, as a marker of M2-TAMs, have been investigated immunohistologically." (PMID 39126553, 2024). "Tregs and macrophages (CD68 and CD163) are more complicated since some data suggested Treg and macrophage infiltration in the tumor microenvironment might be poor prognostic markers, but another study suggested they might be favorable prognostic markers." (PMID 38339307, 2024). "To identify the extent of transcriptome remodeling in HCs from tumors (THC), we extracted the tumor fraction and compared the gene expression profile of THC with tumor epithelial cells (EPCAM+ and KRT8+) and THCs with tumor-associated macrophage/monocyte cells (CD14+ and CD163+)." (PMID 38611120, 2024). "Differences were statistically significant between tumoral LLT1 expression and stroma- and tumor-infiltrating CD68+ macrophages (Kruskal–Wallis test, p = 0.03 and p = 0.001, respectively), and also tumor-infiltrating CD163+ macrophages (Kruskal–Wallis test, p = 0.002)." (PMID 38673902, 2024). "Moreover, CD8+ T cells were in closer proximity to tumor cells and CD163+ macrophages, and PD-L1+ tumor cells and macrophages were closer to PD-1+ cytotoxic T lymphocytes in HPV-positive primary tumors." (PMID 38275860, 2024). "Interestingly, higher expression of these genes is related to higher CD4+, CD8+, and FOXP3+ T cells as well as with higher CD163 macrophages tumor infiltration." (PMID 38790160, 2024). "We further analyzed the expression of CD163+ macrophages and PD-L1+ cells to gain further insight into the expression of antigen-presenting cells (APCs) and inhibitory immune checkpoints within the tumor and TME." (PMID 38781019, 2024). "In addition, overexpression of YAP1 induces the polarization of macrophages into the M2 phenotypes (tumor-associated macrophages) by regulating different genes such as iNOS, MerTK, IL-10, STAT3, CD163, CD206, Arg-1, CD86, and TNF-α in the naive macrophages." (PMID 39630608, 2024). "In addition, a significant direct correlation between high mean H score value of CD163 staining with larger tumor size (p < 0.031) was registered." (PMID 39462379, 2024). "These structures could be visible by staining, including panel I: CD8+ T cells, CD4+ T cells, PD-1+ cells, PD-L1+ cells, Foxp3+ regulatory T cells; and panel II: CD19+ B cells, CD56+ NK cells, CD68+ macrophages, CD163+ M2 macrophages, cytokeratin+ tumor cells." (PMID 38637495, 2024).
tumor (continued). "Moreover, IHC staining of HCC tumor tissues from our cohort also revealed significant correlations of B4GALNT1 levels with the numbers of infiltrating CD163 + TAMs (R2 = 0.06, p = 0.019) and CD4 + T cells (R2 = 0.05, p = 0.038)." (PMID 39616302, 2024). "CD163+macrophages were the immune cells located closest to tumor cells." (PMID 39053947, 2024). "Interestingly, although major macrophage-specific mRNAs (CD68, CD14, and ITGAM) were relatively unchanged, the mRNAs associated with an M2 phenotype (CSFR1, CD163, MS4A4A, and CRC1) were decreased, suggesting a change toward a more M1, anti-tumor status." (PMID 38744944, 2024). "Notably, numbers of ARG1-positive immune cells were significantly reduced by the Hes1 KO, with a decrease in the numbers of tumor-promoting TAMs that were CD163-positive macrophages." (PMID 39702544, 2024). "Additionally, there is evidence of a decreased frequency of CD163+ macrophages in the SLN of patients with BC compared to non-tumour-draining LNs, particularly for invaded SLNs." (PMID 39199652, 2024). "Interestingly, CD163 at the tumor border correlated with all the markers from the middle core and also with PD-L1 expression, whereas CD163 in the center correlated only with CD163 at the periphery." (PMID 39338178, 2024). "This indicates a possible interaction between macrophages and both T cell subsets (CD4+ and CD8+), as well as other macrophages (CD163+), suggesting that macrophages in the tumor center might play a central role in coordinating the immune response." (PMID 39338178, 2024). "Immunohistochemistry reveals CD68, CD163, lysozyme, and CyclinD1 expression in the tumor cells." (PMID 38706599, 2024). "Therefore, macrophages with only or predominant CD163 expression exert protumor action in the tumor as well, however, this effect is counterbalanced by expression of CD68." (PMID 38287290, 2024). "Overall, a lower number of CD163+ TAMs in tumor patients correlated with a higher survival rate." (PMID 39451197, 2024). "In addition to these results, we were able to analyze CD163 protein expression in the tumor tissue, which was correlated with immunotherapy information." (PMID 39015503, 2024). "However, it is important to note that there was also an increase in pro-tumor CD163+ M2 macrophages in the anti-CD47 treatment group." (PMID 38532108, 2024). "In conclusion, our data support the hypotheses that K17 shields tumor cells from CD8+ T cells and recruits tumor promoting CD163+ M2 macrophages, indicating that K17 fundamentally impacts the immune response to PDAC." (PMID 38730319, 2024). "Additionally, G3 tumor grade, stratified CD163 IDR, and absolute CD8 cell density reached statistically significant (p < 0.05) stratification in the Kaplan–Meier analysis of RFS." (PMID 38731992, 2024). "High density of CD3+ (HR: 0.555, p=0.018), CD20+ (HR: 0.482, p=0.002) and CD163+ (HR: 0.514, p=0.039) cell infiltrates was associated with better RFS as well as high levels of PD-L1 and PVR in tumor cells (HR: 0.626, p=0.034 and HR: 0.538, p=0.034, respectively)." (PMID 39723208, 2024). "And the expression levels of CD163 significantly increased in tumor infiltration depth." (PMID 39104717, 2024). "In conclusion, PD-L1 was positively expressed on tumor cells in 52% of CC patients, and could be used as a prognostic predictor, and was closely related to CD163+TAMs infiltration." (PMID 38970071, 2024). "Furthermore, depletion of CD163+ TAMs led to restoration of cytotoxic T-cell and inflammatory monocyte activity, leading to resensitization of tumor cells to anti-PD-1 therapy." (PMID 38033495, 2023). "Similarly, CAMOIP analysis revealed that the M2 macrophage marker, CD163, is significantly higher in tumours with high B7H3 expression." (PMID 37370746, 2023). "Additionally, a set of potential prognostic biomarkers, including CD163 expression in tumor cells, deserve further investigation." (PMID 37509688, 2023).
tumor (continued). "Additionally, the expression of CD163, a M2 macrophages marker, was elevated in tumours with increased B7H3 expression." (PMID 37370746, 2023). "In comparison to non-cancerous colon mucosa (NM), CRC is significantly more infiltrated by CD163+ tumor-infiltrating macrophages (TAMs), including a fraction of immune suppressive TREM2+ macrophages; moreover, a significant reduction of CD3+CD4−CD8− double negative T lymphocytes occurs." (PMID 37370706, 2023). "The patients with GC having a high infiltration of M2 TAMs (CD163) in the tumour stroma and invasive tumour margin often predicted a poor OS, while the distribution of high infiltration of M2 TAMs in the tumour nest was not related to the prognosis of patients." (PMID 37608500, 2023). "In contrast, M2 macrophages, identified by the expression of CD204 (macrophage scavenger receptor class A) or CD163 (macrophage scavenger receptor class B), are considered to promote tumor progression by secreting multiple growth factors, proteolytic enzymes, and proangiogenic molecules." (PMID 36633963, 2023). "In addition, we found that patients with a low CD163/CD68 expression ratio within the tumor significantly benefited from adjuvant chemotherapy compared to patients with a high CD163/CD68 expression ratio within the tumor." (PMID 37208929, 2023). "CD209+ and CD163+ cells were more abundant at the tumor margin." (PMID 37435060, 2023). "Therefore, it reveals CD163+ TAMs to exhibit the best prognostic potential of macrophage subsets in both intra-tumour and stromal OSCC biopsies." (PMID 37397243, 2023). "Quantification of stromal TIM-3+CD163+ TAMs in tumor residues after NAC may represent a new way of identifying patients at high risk of relapse." (PMID 38090569, 2023). "In this case, CD64+CD68+CD163- TAM were dominant in tumor stroma." (PMID 37691949, 2023). "Interestingly, the knockdown of PLXNB3 also reduced the infiltration of CD163-positive M2 TAMs into metastatic niches, illustrating that the promotion effects of tumor cells and TAMs were reciprocal." (PMID 36741230, 2023). "One study reported that increased CD163 + tumor-associated macrophages (TAM) were observed in non-pCR group in LARC patients." (PMID 37953237, 2023). "The authors suggested that the interaction of MCs with these immune cells might be exerting an inhibitory effect in IBC, through suppressing CD8+ T cells, enhancing immunosuppressive CD163+ macrophages, and directly promoting tumor cell growth." (PMID 37190096, 2023). "We found that the frequency of selected cells is significantly higher in the CLR group compared to DII and background at k = 40 (p = 8.1e−8 and p = 0.019, Wilcoxon test, respectively) and composed of mostly tumor cells (15%), CD163+ macrophages (15%), and B cells (8%)." (PMID 37720335, 2023). "It is hypothesized that TAMs at the invasive front in CLM exhibit an immunosuppressive role by PD-L1 expression.The tumor periphery also had relatively higher density of CD68+CD163+CD206neg M2 macrophages than the center." (PMID 37637998, 2023). "In addition to FOXP3+ Tregs, marginal tumor regions have more subpopulations with an immunosuppressive phenotype, including CD163+ macrophages, CD11b+ neutrophils, and CD274 (PD-L1)+ tumor cells." (PMID 37529035, 2023). "Interestingly, we observed almost complete polarization of macrophages in CD163+ M2-macrophages in the tumor margin." (PMID 36836239, 2023). "LRP1B expression in TCs stimulates the infiltration of CD4+ and CD8+ T cells and raises the ratio of CD86/CD163, which may be due to an increase in tumor immunogenicity to achieve immune activation and prevent disease progression." (PMID 38136305, 2023). "Moreover, OR2805, an anti-CD163 antibody, has been developed and is now in phase I/II clinical trials as a single agent or in combination with a PD-1 antibody against multiple tumor types (NCT05094804)." (PMID 37180125, 2023).